MYO1H (myosin IH)
Description:
Myosins are actin-based motor molecules with ATPase activity. Unconventional myosins serve in intracellular movements. Their highly divergent tails are presumed to bind to membranous compartments, which would be moved relative to actin filaments (By similarity).
Synonyms: FLJ37587; CCHS2
Gene: Protein-coding gene on chromosome 12 (109,347,900 to 109,455,523, forward strand). Ensembl gene ENSG00000174527.
Genetic constraint (gnomAD): Loss-of-function variants: 76 observed, 95 expected, observed/expected ratio (o/e) 0.8, 90% interval 0.66 to 0.97. The upper end of that interval is the gene's LOEUF score, 0.97, which puts it in group 4 of 6, group 1 being the genes least tolerant of losing a copy. Missense variants: 961 observed, 1,006.2 expected, observed/expected ratio (o/e) 0.96, 90% interval 0.9 to 1.01. Synonymous variants: 370 observed, 383.27 expected, observed/expected ratio (o/e) 0.97, 90% interval 0.89 to 1.05.
Homologues: Orthologues: chimpanzee MYO1H (99% identical), macaque MYO1H (96% identical), guinea pig MYO1H (92% identical), dog MYO1H (92% identical), rat Myo1h (87% identical), rabbit MYO1H (87% identical), mouse Myo1h (87% identical), pig MYO1H (85% identical), tropical clawed frog myo1h (70% identical), zebrafish myo1hb (65% identical), zebrafish myo1ha (64% identical). Paralogues in human: MYO1C (60% identical), MYO1B (42% identical), MYO1A (39% identical), MYO1D (39% identical), MYO1G (38% identical), MYO7B (32% identical), MYH7 (32% identical), MYO7A (32% identical), MYH3 (32% identical), MYH2 (31% identical), MYH6 (31% identical), MYH4 (31% identical), and 32 more.
Diseases named in the same sentence as MYO1H in open-access papers:
MYO1H is named in the same sentence as 3 diseases in open-access papers, as found by Europe PMC text mining. Sharing a sentence is not in itself a finding about the gene and the disease. The quoted sentences say what the papers report.
small cell lung carcinoma (1 paper, 2021). Small cell lung cancer (SCLC) is a highly aggressive malignant neoplasm, accounting for 10-15% of lung cancer cases, characterized byrapid growth, and early metastasis.
infection (1 paper, 2020). The state of being infected such as from the introduction of a foreign agent such as serum, vaccine, antigenic substance or organism. "This cluster contained Acta1, encoding smooth muscle actin, as well as the actin crosslinking protein gene Actn3 and two myosin genes (Myo1h and Myh2), suggesting that both infection and Muc1 knockout disrupt the cytoskeleton." (PMID 32793510, 2020).
tumor (1 paper, 2021). "The expression of GNG8, MYO1H, and TNFRSF13B was significantly down-regulated, while the expression of SYT14 and FOXA2 was significantly up-regulated in the samples with higher tumor stage, the samples with high risk had lower overall survival rates." (PMID 34322156, 2021). "Moreover, the expression of GNG8, MYO1H, and TNFRSF13B was significantly down-regulated, while the expression of SYT14 and FOXA2 was significantly up-regulated in the samples with higher tumor stage." (PMID 34322156, 2021).